HHEX (hematopoietically expressed homeobox)
Description:
Recognizes the DNA sequence 5'-ATTAA-3' (By similarity). Transcriptional repressor (By similarity). Activator of WNT-mediated transcription in conjunction with CTNNB1. Establishes anterior identity at two levels; acts early to enhance canonical WNT-signaling by repressing expression of TLE4, and acts later to inhibit NODAL-signaling by directly targeting NODAL (By similarity). Inhibits EIF4E-mediated mRNA nuclear export. May play a role in hematopoietic differentiation.
Synonyms: HEX; PRH; PRHX; HOX11L-PEN; HMPH
Tractability: PROTAC: ubiquitination databases record sites on it.
Gene: Protein-coding gene on chromosome 10 (92,689,903 to 92,695,647, forward strand). Ensembl gene ENSG00000152804.
Subcellular location: Nucleus; Nucleus, nuclear body; Cytoplasm
Subcellular location (Human Protein Atlas): Nucleoplasm; Nuclear bodies
Pathways (Reactome):
Developmental Biology: Developmental Lineage of Multipotent Pancreatic Progenitor Cells; POU5F1 (OCT4), SOX2, NANOG repress genes related to differentiation
Gene Ontology:
Molecular function: DNA binding, bending; DNA-binding transcription activator activity, RNA polymerase II-specific; DNA-binding transcription factor binding; DNA-binding transcription repressor activity, RNA polymerase II-specific; eukaryotic initiation factor 4E binding; protein binding; protein homodimerization activity; RNA polymerase II cis-regulatory region sequence-specific DNA binding; sequence-specific DNA binding; transcription cis-regulatory region binding; translation regulator activity; DNA-binding transcription factor activity, RNA polymerase II-specific; TBP-class protein binding; DNA binding
Biological process: DNA conformation change; negative regulation of cytoplasmic translational initiation; negative regulation of DNA-templated transcription; negative regulation of transcription by RNA polymerase II; positive regulation of canonical Wnt signaling pathway; positive regulation of DNA-templated transcription; positive regulation of transcription by RNA polymerase II; protein localization to nucleus; regulation of leukocyte proliferation; regulation of mRNA export from nucleus; anterior/posterior pattern specification; B cell differentiation; cell differentiation; negative regulation of angiogenesis; negative regulation of vascular endothelial growth factor receptor signaling pathway; positive regulation of Wnt signaling pathway; regulation of transcription by RNA polymerase II; regulation of DNA-templated transcription
Cellular component: cytoplasm; nucleus; protein-DNA complex; chromatin; nuclear body
Genetic constraint (gnomAD): Loss-of-function variants: 8 observed, 22.11 expected, observed/expected ratio (o/e) 0.36, 90% interval 0.21 to 0.65. The upper end of that interval is the gene's LOEUF score, 0.65, which puts it in group 2 of 6, group 1 being the genes least tolerant of losing a copy. Missense variants: 323 observed, 327.79 expected, observed/expected ratio (o/e) 0.99, 90% interval 0.9 to 1.08. Synonymous variants: 160 observed, 139.44 expected, observed/expected ratio (o/e) 1.15, 90% interval 1.01 to 1.31.
Homologues: Orthologues: chimpanzee HHEX (100% identical), macaque HHEX (99% identical), dog HHEX (98% identical), pig HHEX (96% identical), tropical clawed frog hhex (74% identical), guinea pig Hhex (33% identical).